UCN2 (urocortin 2)
Diseases named in the same sentence as UCN2 in open-access papers (continued):
Sharing a sentence is not in itself a finding about the gene and the disease.
endometrial cancer (1 paper, 2017). Primary or metastatic malignant neoplasm involving the endometrium (mucous membrane that lines the endometrial cavity). "Further work is required to understand the mechanisms through which UCN1 suppresses endometrial cancer cell migration, and to characterize the role of UCN2, UCN3, and the CRF‐BP in endometrial cancer." (PMID 28109061, 2017).
endometriosis (1 paper, 2019). The growth of functional endometrial tissue in anatomic sites outside the uterine body. "Both UCN2 and UCN3 expression levels were significantlylower in women with endometriosis when comparedwith healthy women." (PMID 30644237, 2019). "In women suffering from endometriosis, theexpression of UCN, UCN2 and UCN3 transcripts wasthe same in the secretory and the proliferative phases,whereas in healthy women UCN levels differed betweenthe two phases." (PMID 30644237, 2019).
Hypoglycemia (1 paper, 2019). A decreased concentration of glucose in the blood. "Therefore, it is plausible that gluconeogenesis in hepatocytes are increased to prevent hypoglycemia in normal mice that received Ucn2 gene transfer." (PMID 31790421, 2019). "Therefore, it is plausible that gluconeogenesis in hepatocytes are increased to prevent hypoglycemia in normal mice that received AAV8.Ucn2." (PMID 31790421, 2019). "We have previously showed that AAV8.Ucn2 gene transfer increases glucose disposal and decreases fasting glucose without hypoglycemia in normal C57BL/6 mice." (PMID 31790421, 2019). "AAV8.Ucn2 gene transfer reduced blood glucose level by 24%, but it did not induce hypoglycemia, which suggests that AAV8.Ucn2 was able to regulate glucose homeostasis." (PMID 31790421, 2019).
inflammatory skin disease (1 paper, 2023). Inflammatory skin disorders covers a broad category that includes many conditions ranging in severity, from mild itching to grave medical health complications These disorders are common in people of all ages and races. "Overall, this study sheds new light on putative mechanisms of immunoregulatory skin DC subsets, evokes the neuroendocrine-immune axis as a possible mediator of human solar UVB-mediated skin immune homeostasis, and indicates the UCN2 pathway as a therapeutic target in inflammatory skin disease." (PMID 37860766, 2023).
myocardial infarction (1 paper, 2024). Gross necrosis of the myocardium, as a result of interruption of the blood supply to the area, as in coronary thrombosis. "Gal-3 seems to not be a perfect marker for patients after myocardial infarction, but similarly to Ucn-2, more studies are necessary to discover its practical use." (PMID 38396869, 2024).
pancreatitis (1 paper, 2019). Inflammation of the pancreas. "At high doses of caerulein that cause pancreatitis like symptoms, UCN2 reduced caerulein-evoked [Ca2+]i by 50% and also prevented the massive redistribution of F-actin." (PMID 31100090, 2019). "In contrast to UCN1 levels, which have been shown to increase in caerulein-induced pancreatitis, in this study, UCN2 levels decreased." (PMID 31100090, 2019). "In conclusion, we show that UCN2 attenuated experimental pancreatitis; its protective effects including anti-inflammatory and anti-necrotic effects are potentially due the effect of UNC2 on activation of NF-κB pathway." (PMID 31100090, 2019). "Here, we show that UCN2 ameliorated caerulein-induced pancreatitis measured by reductions in levels of serum amylase and lipase; and tissue measurements of cell necrosis, immune cell infiltration, as well as by inhibition of NF-κB activation." (PMID 31100090, 2019). "However, the role of UCN2 in pancreatitis, the ligand that exclusively binds and activates CRF2 receptor, has not been characterized." (PMID 31100090, 2019). "Interestingly, 100nM UCN2 prevented increases in [Ca2+]i at 0.1nM caerulein and reduced responses by 50% at 1.0nM caerulein, a dose that results in prolonged and sustained increases in [Ca2+]i and pancreatitis responses." (PMID 31100090, 2019). "UCN2 is potent vasodilator and one possible mechanism by which it could influence pancreatic function is by increasing blood flow to the organ, which is known to be compromised in pancreatitis." (PMID 31100090, 2019).
pulmonary arterial hypertension (1 paper, 2024). Pulmonary arterial hypertension (PAH) is a group of diseases characterized by mean pulmonary artery pressure >20 mmHg and elevated pulmonary arterial resistance leading to right heart failure. "An increase in Ucn-2 is seen in HF, left ventricular systolic dysfunction, non-ischemic dilated cardiomyopathy, and pulmonary arterial hypertension (PAH)." (PMID 38396869, 2024).
Stroke (1 paper, 2025). Sudden impairment of blood flow to a part of the brain due to occlusion or rupture of an artery to the brain. "Specifically, PPARα KO led to increased expression levels of Gadd45b, Nppa, Hdc, Lcn2, Il6, Sox4, Marcksl1, Saa3, Ucn2, Met, Dusp10, Elovl7, Ngf, C3, Il11, Hmox1, Alox5, Tnfsf9, Angptl4, Plin2, H19, Csf2rb, Atf3, and Col7a1 following stroke." (PMID 40362325, 2025).
ventricular tachycardia (1 paper, 2023). A disorder characterized by an electrocardiographic finding of three or more consecutive complexes of ventricular origin with a rate greater than a certain threshold (100 or 120 beats per minute are commonly used). "On the other hand, the frequent sinus tachycardia or the rarely developing ventricular tachycardia elicited by the Ucn2 treatment may present a remarkable cardiovascular complication." (PMID 37240340, 2023).
tumor (12 papers, 2009 to 2025). "In contrast, risk genes, except urocortin-2 (UCN2), were significantly upregulated in tumor tissues." (PMID 36479115, 2022). "Specifically, in vivo and in vitro studies found that UCN2/CRFR2 activation inhibited tumor vascularization and cell proliferation and invasion." (PMID 29499655, 2018). "This contributes to the comprehension of the tumor-promoting effects of stress molecules and designates Ucn2/3-CRF2 tandem as a target to prevent CRC progression and aggressiveness." (PMID 24260200, 2013). "Previous studies have shown that Ucn2 could suppress tumor growth predominantly by the inhibition of tumor vascularization, but also potentially through direct effects on tumor cell proliferation." (PMID 40429988, 2025). "In our experimental model, ectopic induction of CRHR2 in CRC cell lines resulted in dramatic inhibition of the endogenous Ucn2 levels, while the receptor activation by exogenous Ucn2 reduced critically the tumor survival and expansion in vitro and in vivo in xenograft mouse models." (PMID 31614860, 2019). "In prostatic cells it has been found that CRH and Ucn2 affect apoptosis of tumor cells." (PMID 27695045, 2016). "Interestingly, ligands of the other CRF receptor, the CRF2, have been found to suppress tumor growth while the expression of the CRF2-specific endogenous ligand UCN2 in tumors results in reduced angiogenesis and suppression of tumor growth." (PMID 19490624, 2009). "Additionally, it was found that YY1 is negatively regulated by corticotropin-releasing hormone receptor-2 (CRHR2)/Urocortin-2 (Ucn2) signaling, which can result in transcriptional de-repression of Fas and can resensitize the tumor to anti-Fas antibody-mediated apoptosis." (PMID 38539569, 2024). "Therefore, we hypothesized that COL7A1-UCN2 may down-regulate the mRNA expression of both COL7A1 and UCN2 in LC tissues and that such down-regulation may promote tumor invasion via EMT regulation." (PMID 29499655, 2018). "Therefore, this TIC potentially down-regulated the expression of the COL7A1 and UCN2 genes during and after chimera fusion; and it is thereby associated with poor clinical prognosis because both COL7A1 and UCN2 possessed explicit suppressor roles in tumor EMT regulation." (PMID 29499655, 2018). "One putative tumor-specific peptide with the sequence TTNARILAR, derived from urocortin-2 (UCN2) was downregulated upon MAPK-signaling inhibition in Ma-Mel-63a cells." (PMID 39835134, 2024). "Concurrent alterations in apoptotic behavior and AKT pathway signaling of tumor cells have also been observed following treatment by CRH and UCN2." (PMID 27695045, 2016). "We have first performed qPCR for CRF2α (the major CRF2 isoform of colonic epithelium), and Ucn2/3 in normal and CRC tissues of 30 patients, to better understand their regulation during tumor progression." (PMID 24260200, 2013). "We could not elucidate the intrinsic genetic and epigenetic mechanism responsible for COL7A1-UCN2 generation; however, both the COL7A1 and UCN2 genes had explicit suppressor roles in tumor regulation, specifically the regulation of the epithelial-mesenchymal transition (EMT)." (PMID 29499655, 2018).
cancer (4 papers, 2018 to 2023). A tumor composed of atypical neoplastic, often pleomorphic cells that invade other tissues. "We have further identified the CRFR2/Ucn2 signaling as a critical negative regulator in sustaining chronic inflammation and promoting cancer development and aggressiveness in the colon." (PMID 34207031, 2021).
UCN2 also shares sentences with these, for which no sentence is quoted: type 2 diabetes (3 papers); colon carcinoma (2); lung carcinoma (2); acute pancreatitis (1); aneurysm (1); Arrhythmia (1); Cachexia (1); differentiated thyroid carcinoma (1); epithelial ovarian cancer (1); fibrosis (1); generalized anxiety disorder (1); gestational diabetes (1); Hyperglycemia (1); ileitis (1); infection (1); intracranial aneurysm (1); ischemia (1); laryngeal carcinoma (1); Lewis lung carcinoma (1); non-small cell lung carcinoma (1); ovarian tumors (1); Pancreatic Cancer (1); papillary thyroid cancer (1); Premature rupture of membranes (1); prostate carcinoma (1); prostate tumors (1); retinal degeneration (1).